UHRF1 (ubiquitin like with PHD and ring finger domains 1)
Diseases named in the same sentence as UHRF1 in open-access papers (continued):
Sharing a sentence is not in itself a finding about the gene and the disease.
astrocytoma (4 papers, 2010 to 2021). "Significant overexpression of UHRF1 was observed in cancerous tissues as compared with normal cells showing the possibility to use this differential expression of UHRF1 as a diagnostic marker for astrocytoma." (PMID 28881702, 2017). "Representational difference analysis (RDA) of different pathological grades of astrocytoma revealed UHRF1 and four other genes to be differentially expressed in astrocytoma cancer tissues." (PMID 28881702, 2017). "Recently, we showed that activation of CD47 in two human astrocytoma cell lines, upregulated the expression of UHRF1 with subsequent downregulation of p16INK4A." (PMID 27839516, 2016). "Similarly, our recent study suggests that activation of highly expressed membrane integrin CD47 in astrocytoma activates NFκB-mediated signaling and UHRF1 expression, which in turn represses p16, thereby strengthening the tumor promoter role of UHRF1." (PMID 28881702, 2017). "Moreover, the existence of (a) molecular mechanism(s) inhibiting the Dnmt1/PCNA/UHRF1 interaction is also supported by the paradoxical situation seen in astrocytoma cells." (PMID 20613874, 2010). "Indeed, the astrocytoma cells harbor a low level of Dnmt1/PCNA/UHRF1 interaction, whereas these cells, highly proliferative, are supposed to harbor a high level of the Dnmt1/PCNA/UHRF1 interaction according to the idea that the maintenance DNA methylation is a DNA replication-dependent process." (PMID 20613874, 2010). "In human astrocytoma cells and Jurkat cells, TQ was shown to induce a concentration- and time-dependent degradation of UHRF1 and α/β tubulin, while no similar effect was observed in normal human fibroblast cells, again suggesting that TQ exerts a selective effect on UHRF1." (PMID 33922029, 2021). "Recently, we showed that CD47 activation using 4 N1 (CD47 agonist) peptide induced a significant increase in the expression of both UHRF1 gene and protein in human astrocytoma cell lines U87 and CCF-STTG1 (Grade IV) without affecting their expression in normal human astrocytes NHA." (PMID 27839516, 2016).
gallbladder cancer (4 papers, 2017 to 2024). "In gallbladder cancer, UHRF1 depletion is associated with cell apoptosis and cell cycle arrest." (PMID 30352833, 2018). "In this study, we suppose to investigate the clear functions of YTHDF1 and m6A‐dependent functions on regulating m6A/UHRF1 axis in gallbladder cancer progression." (PMID 38683130, 2024). "All this information suggests an oncogenic role of UHRF1 in gallbladder cancer and increased expression of UHRF1 as an independent biomarker for diagnosis and a therapeutic target of gallbladder cancers." (PMID 28881702, 2017). "UHRF1 has also been proposed as a biomarker and potential therapeutic target for gallbladder cancer, which is well known for its poor prognosis and high mortality rate." (PMID 28881702, 2017).
glioblastoma (4 papers, 2016 to 2025). The most malignant astrocytic tumor (WHO grade IV). "Interestingly, CD47 knockdown using siRNA in U87 cell line induced a significant downregulation of UHRF1 indicating that CD47 positively controls the expression of UHRF1 in glioblastoma cells." (PMID 27839516, 2016).
infertile (4 papers, 2019 to 2023). "Conditional deficiency of Uhrf1 in differentiated spermatogonia results in meiotic defects and infertility." (PMID 37667177, 2023). "We showed that the conditional knockout (cKO) of UHRF1 in either primordial or growing oocytes causes infertility but differentially affects early embryonic development." (PMID 33634103, 2020). "Both conditional knockouts (cKOs) caused infertility, but displayed different early embryonic development defects, demonstrating the crucial role of maternal UHRF1 in reproduction." (PMID 33634103, 2020). "Consistent with this infertile phenotype, testis size from Uhrf1 cKO mice was significantly smaller than their controls by ~30%." (PMID 31624244, 2019). "The UHRF1-deficient male mice were apparently normal in growth (data not shown) but infertile." (PMID 32081844, 2020).
lung squamous cell carcinoma (4 papers, 2019 to 2022). "We find that UHRF1 is predominantly overexpressed in lung squamous cell carcinoma (SCC)." (PMID 32495469, 2020).
multiple myeloma (4 papers, 2020 to 2022). "UHRF1 overexpression promoted multiple myeloma cell proliferation and reduced multiple myeloma cells that are more resistant to berberine, although silencing of UHRF1 with siRNA reduced berberine-induced cytotoxicity." (PMID 36144625, 2022). "A recent study showed that berberine, a botanical alkaloid, targets UHRF1 by binding UHRF1 directly in its tandem tudor domain‐plant homeodomain domain and induces UHRF1 degradation in multiple myeloma cells." (PMID 32840881, 2021). "The botanical alkaloid BBR has also been identified as a novel drug for the treatment of multiple myeloma (MM) through targeting the molecular mechanism UHRF1 (ubiquitin-like with PHD and RING Finger domains 1)." (PMID 34835969, 2021). "UA might interact with USP7 in RPMI8226 human myeloma cells and could inhibit myeloma cell proliferation (IC50 = 6.56 μmol/L), accompanied by reductions in USP7 substrates such as MDM2, UHRF1, and DNMT1 related to the inhibition of USP7." (PMID 34835969, 2021).
thyroid cancer (4 papers, 2017 to 2024). "It is yet to be seen how UHRF1-mediated overexpression of cytokines causes inflammatory reaction and metastasis in thyroid cancer." (PMID 35996525, 2022). "UHRF1 levels were significantly higher in both differentiated and poorly differentiated cancer cells as compared with normal cells, suggesting a good diagnostic value for UHRF1 in thyroid cancers." (PMID 28881702, 2017). "Although results have indicated that suppression of UHRF1 could decrease the metastasis of thyroid cancer cells, it is more important to understand the underlying mechanisms that UHRF1 promotes the metastasis." (PMID 35996525, 2022). "Coimmunoprecipitation assays and immunofluorescence staining assays were used to elucidate the potential mechanisms of UHRF1 in promoting the metastasis of thyroid cancer." (PMID 35996525, 2022). "In this study, we aimed to investigate the metastatic function and the potential mechanisms of UHRF1 in thyroid cancer." (PMID 35996525, 2022). "Our previously published study confirmed that UHRF1 promoted the dedifferentiation of thyroid cancer." (PMID 35996525, 2022). "Here, we conducted this study to investigate the metastatic function and mechanisms of UHRF1 in thyroid cancer." (PMID 35996525, 2022). "According to our previous and present results in thyroid cancer, UHRF1 should be an essential gene in dedifferentiation and metastasis." (PMID 35996525, 2022). "In this study, we demonstrated that UHRF1 promoted the metastasis of thyroid cancer cells through a potential mechanism that UHRF1 directly bound and activated c-Jun/AP-1." (PMID 35996525, 2022). "To study how UHRF1 promoted thyroid cancer cell metastasis, we analyzed the transcription levels of key regulators of immunoregulatory cytokine interleukin 6 (IL-6) and the macrophage migration inhibitory factor (MIF) in BCPAP by qPCR." (PMID 35996525, 2022). "To examine the possible role of UHRF1 in thyroid cancer progression, we stably knocked down the expression of UHRF1 in ATC cell lines, 8505c and Cal-62." (PMID 30174788, 2018). "Through analyzing with GEO2R on the website, we found that samples collected from thyroid cancer patients displayed a significantly increased UHRF1 level compared with normal controls." (PMID 30174788, 2018). "Together, these findings indicated that UHRF1 was critical to the proliferation of human ATC cells and that UHRF1 inhibition reduced thyroid cancer progression." (PMID 30174788, 2018). "Our previous study confirmed that UHRF1 protein was overexpressed in thyroid cancer cells, which meant UHRF1 might also be a critical gene for thyroid cancer in predicting survival and treatment responses." (PMID 35996525, 2022). "Our results suggest that UHRF1 could induce the metastasis of thyroid cancer, and the potential signaling pathway might be that UHRF1 activates c-Jun/AP-1 to increase the expression of IL-6 and MIF." (PMID 35996525, 2022). "In order to identify whether UHRF1 induces metastasis in thyroid cancer, we overexpressed UHRF1 in the well-differentiated thyroid cancer cell line BCPAP." (PMID 35996525, 2022). "Consistently, overexpression of UHRF1 promoted the proliferation of thyroid cancer cells." (PMID 30174788, 2018). "Similar findings were reported in thyroid cancers cells as microarray analysis showed significant upregulation of UHRF1 to identify gene expression profile that favors the progression of well differentiated tumors to aggressive, poorly differentiated or undifferentiated cancer cells." (PMID 28881702, 2017). "Accordingly, UHRF1-c-Jun/AP-1 complex could be a potential treatment target for thyroid cancer." (PMID 35996525, 2022). "However, the role of UHRF1 in mediating metastasis in thyroid cancer remains unexplored." (PMID 35996525, 2022). "However, the role and molecular mechanisms of UHRF1 in driving thyroid cancer metastasis remain unknown." (PMID 35996525, 2022).
thyroid cancer (continued). "Our previously published study showed that UHRF1 was significantly overexpressed in PTC and ATC compared with normal thyroid cancer tissues, and suppressing UHRF1 decreased the proliferation of ATC and induced differentiation." (PMID 35996525, 2022). "Finally, we deduced that UHRF1-c-Jun/AP-1 complex could promote metastasis in thyroid cancer." (PMID 35996525, 2022). "Based on these studies, the signaling pathway that UHRF1 plus c-Jun/AP-1 increased the expression of IL-6 and MIF might be a potential key mechanism of thyroid cancer metastasis." (PMID 35996525, 2022). "Targeting UHRF1 in these cells resulted in suppression of dedifferentiation and stem cell marker expression such as CD97, SOX2, OCT4 and NANOG, highlighting UHRF1 as an attractive target for thyroid cancer therapy." (PMID 28881702, 2017). "Thus, inhibition of UHRF1 contribute to suppression of cytokines transcription (IL-8, TGF-α and TNF-α), which might relieve the inflammatory reaction in advanced thyroid cancer patients." (PMID 30174788, 2018).
endometrial cancer (3 papers, 2016 to 2022). Primary or metastatic malignant neoplasm involving the endometrium (mucous membrane that lines the endometrial cavity). "An increased cellular proliferation of endometrial cancer was shown to be linked to UHRF1-mediated H3R8 di-methylation of the SOCS3 and 3OST2 promoter." (PMID 36077796, 2022). "In another study, it has been reported that UHRF1 associates with PRMT5 (Protein arginine N-methyltransferase 5) in endometrial carcinoma." (PMID 27839516, 2016). "AR target genes such as XBP1, MYC, ZBTB16, and UHRF1 were previously reported to be induced by DHT treatment in AR-positive endometrial cancer MFE-296 cells." (PMID 29642629, 2018). "It was also reported that XBP1 and UHRF1 are related to tumor growth or carcinogenesis in endometrial cancer." (PMID 29642629, 2018).
myeloid leukemia (3 papers, 2022 to 2025). A clonal proliferation of myeloid cells and their precursors in the bone marrow, peripheral blood, and spleen. "Lastly, we identified a UHRF1 inhibitor, UF146, and demonstrated its significant therapeutic efficacy in the myeloid leukemia PDX model." (PMID 36302855, 2022).
prostate tumor (3 papers, 2018 to 2025). "We analyzed FOXM1 and UHRF1 protein expression levels in 546 prostate tumor tissues using the TCGA data." (PMID 29752436, 2018). "UHRF1 and EZH2 were previously linked for their paralleled functions in keratinocyte self-renewal and for their positive correlation in human prostate tumor samples." (PMID 35169042, 2022).
small cell lung carcinoma (3 papers, 2022 to 2024). Small cell lung cancer (SCLC) is a highly aggressive malignant neoplasm, accounting for 10-15% of lung cancer cases, characterized byrapid growth, and early metastasis. "UHRF1 expression levels are significantly elevated in small cell lung cancer (SCLC) and are closely associated with poor prognosis." (PMID 38725075, 2024). "Specifically, in small cell lung cancer (SCLC), UHRF1 promotes SCLC proliferation through its interaction with the yes-associated protein 1 (YAP1), preventing YAP1 ubiquitination and degradation." (PMID 39051184, 2024).
anaplastic thyroid cancer (2 papers, 2018 to 2022). "In this study, we found that overexpression of UHRF1 promoted the metastasis of papillary thyroid cancer cells, and suppression of UHRF1 decreased the metastasis of anaplastic thyroid cancer cells." (PMID 35996525, 2022).
Arthritis (2 papers, 2022 to 2023). Inflammation of a joint. "This study demonstrated that UHRF1 expressed in RA SFs can contribute to negative feedback mechanisms that suppress multiple pathogenic events in arthritis, suggesting that targeting UHRF1 could be one of the therapeutic strategies for RA." (PMID 35472067, 2022). "Collectively, these data demonstrated that UHRF1 affects arthritis pathogenesis in a suppressive manner by regulating Th17 recruitment and apoptosis of SFs both in murine models of arthritis and in human RA." (PMID 35472067, 2022). "To assess Uhrf1 localization in synovial tissue, we performed immunofluorescence staining of tissue sections from arthritis model mice." (PMID 35472067, 2022). "To understand physiological functions of Uhrf1 under arthritis conditions, we next established SF-specific Uhrf1 conditional knockout mice (Uhrf1ΔCol6a1)." (PMID 35472067, 2022). "UHRF1 expression was remarkably upregulated in synovial fibroblasts (SFs) from arthritis model mice and patients with RA." (PMID 35472067, 2022). "Upregulation of Uhrf1 mRNA was found not only in CAIA ankle but also in tissue from K/BxN serum transfer arthritis (STA) mice by RT-qPCR." (PMID 35472067, 2022). "Collectively, our finding that Ryuvidine treatment ameliorated arthritis provides support for the ability of UHRF1 stabilization to inhibit expression of multiple exacerbating factors in RA." (PMID 35472067, 2022). "Collectively, these data demonstrated that Uhrf1 expressed in SFs, but not in synovial macrophages, plays a role in suppressing arthritis pathogenesis through negative feedback mechanisms associated with various arthritis pathologies." (PMID 35472067, 2022). "However, our findings showed that arthritis phenotypes that are dependent on UHRF1 expression levels were largely common between humans and mice." (PMID 35472067, 2022). "SF-specific deletion of Uhrf1 exacerbates arthritis pathogenesis." (PMID 35472067, 2022). "Finally, Ryuvidine administration stabilized UHRF1 ameliorated arthritis pathogeneses in a mouse model of RA." (PMID 35472067, 2022). "Our integrative analyses of the transcriptome and methylome of synovial tissue from a murine arthritis model and patients with RA showed that CCL20 is a common UHRF1 target gene among cytokine-, RA-, and antiapoptosis-related genes." (PMID 35472067, 2022). "Thus, we assessed whether Uhrf1 stabilization can improve arthritis pathogenesis." (PMID 35472067, 2022). "The function of UHRF1 in maintenance of DNA methylation is thought to be mediated through DNMT1, although whether suppressive functions of Uhrf1 in arthritis can be completely mediated through Dnmt1 is unclear." (PMID 35472067, 2022).
autoimmune disease (2 papers, 2021 to 2024). A disorder resulting from loss of function or tissue destruction of an organ or multiple organs, arising from humoral or cellular immune responses of the individual to their own tissue constituents. "These novel findings suggest that UHRF1 may play an important role in Tfh cells mediated autoimmune diseases." (PMID 33568199, 2021). "The targeted inhibition of UHRF1 by DPPA3 or PRMT6 proteins may mitigate the suppressive impact of DNMTs on FOXP3+Tregs, thereby offering promising prospects for the treatment of autoimmune diseases." (PMID 39144146, 2024). "Targeted inhibition specifically against UHRF1 may provide novel therapeutic opportunities for autoimmune diseases without affecting Tregs survival." (PMID 39144146, 2024).
Burkitt lymphoma (2 papers, 2020 to 2024). A rare form of malignant mature B-cell non-Hodgkin lymphoma. "One CRISPR/Cas9 screen demonstrated that the ubiquitin ligase ubiquitin-like PHD and RING finger domain-containing protein 1 (UHRF1) and DNA methyltransferases (DNMT1 and DNMT3B) are necessary for the restriction of EBV latency III-associated oncoproteins in Burkitt lymphoma." (PMID 32916819, 2020). "Furthermore, DNA methylation-mediated repression of LMP1 expression in EBV-superinfected Burkitt lymphoma cell lines in vitro is initiated by the DNMT3B de novo methyltransferase and maintained by the DNMT1/UHRF1 maintenance methylation complex." (PMID 38620028, 2024).
cholangiocarcinoma (2 papers, 2024 to 2025). A carcinoma that arises from the intrahepatic biliary tree (intrahepatic cholangiocarcinoma) or from the junction, or adjacent to the junction, of the right and left hepatic ducts (hilar cholangiocarcinoma). "This study demonstrated that cholangiocarcinoma progression was suppressed by restoring miR-1 expression, suggesting that UHRF1 expression is involved in cholangiocarcinoma progression." (PMID 41373864, 2025). "We evaluated the effects of STUB1/UHRF1 on cholangiocarcinoma by utilizing a primary CCA mouse model." (PMID 39267107, 2024).
chronic lymphocytic leukaemia (2 papers, 2018). "The polyphenol-rich Aronia melanocarpa juice and Vaccinium myrtillus extract (Antho 50) also showed down-regulation of UHRF1 in Jurkat cells and chronic lymphocytic leukemia cells, respectively." (PMID 30171426, 2018).
esophageal adenocarcinoma (2 papers, 2018). A malignant tumor with glandular differentiation arising predominantly from Barrett mucosa in the lower third of the esophagus. "Leptin was reported to promote the increase of esophageal adenocarcinoma OE19 cell proliferation, and the effect was observed to be inhibited by adiponectin receptor axis-mediated suppression of ubiquitin-like with PHD and ring finger domains 1 (UHRF1)." (PMID 29682217, 2018).
esophageal cancer (2 papers, 2016 to 2019). A primary or metastatic malignant neoplasm involving the esophagus. "First, we measured UHRF1 mRNA expression levels by qRT-PCR in 16 frozen esophageal cancer tissues and matched normal mucosa." (PMID 27507047, 2016). "Our study also supports an epigenetic role of UHRF1 in esophageal cancer." (PMID 27507047, 2016). "UHRF1 mRNA expression in 16 frozen esophageal cancer tissues did not correlate with UHRF1 protein expression in FFPE sections of the same cases by IHC." (PMID 27507047, 2016). "Notably, 2i treatment also markedly down-regulated the levels of UHRF1 and DNMT1 proteins in all esophageal cancer cells (KYSE150, KYSE410, KYSE140, KYSE520, KYSE30, and KYSE450) with the only one exception of KYSE510, in which UHRF1 protein level was unchanged." (PMID 30696879, 2019). "We found that for 7 esophageal cancer cell lines PD0325901 treatment down-regulated both UHRF1 and DNMT1 at the level of proteins and mRNAs in all lines except KYSE510, a result that is essentially identical to that of 2i on UHRF1 and DNMT1 proteins and mRNAs in these cells." (PMID 30696879, 2019).